KCNK16 (potassium two pore domain channel subfamily K member 16)
Description:
K(+) channel that conducts voltage-dependent outward rectifying currents upon membrane depolarization. Voltage sensing is coupled to K(+) electrochemical gradient in an 'ion flux gating' mode where outward but not inward ion flow opens the gate. Homo- and heterodimerizes to form functional channels with distinct regulatory and gating properties. In pancreatic islets, conducts K(+) countercurrents for Ca(2+) release from the endoplasmic reticulum (ER) and regulates the frequency and duration of cytosolic Ca(2+) oscillations coupled to secretion of pancreatic hormones. In pancreatic beta cells, drives ER Ca(2+) efflux, which in turn activates Ca(2+)-dependent plasma membrane K(+) slow currents and cytosolic Ca(2+) influx, overall contributing to synchronous cytosolic Ca(2+) oscillations. Limits glucose-induced cytosolic Ca(2+) oscillations coupled to second-phase INS secretion. Contributes to beta cell adaptation to acute inflammation by maintaining normal cytosolic Ca(2+) levels and INS secretion (By similarity). May regulate beta cell mitochondrial Ca(2+) levels either indirectly via ER Ca(2+) efflux or directly by hyperpolarizing the mitochondrial membrane potential. Limits mitochondrial Ca(2+) oscillations and ATP production involved in glucose homeostasis upon metabolic stress (By similarity). In pancreatic delta cells, limits Ca(2+)-induced Ca(2+)-release involved in somatostatin secretion and modulates islet paracrine signaling involved in glucagon secretion. Permeable to other monovalent cations such as Rb(+) and Cs(+) (By similarity).
Synonyms: TALK-1; TALK1; K2p16.1
Tractability: Small molecule: it belongs to a druggable protein family. Antibody: UniProt places it where antibodies can reach, with high confidence; its Gene Ontology location is reachable by antibodies, with high confidence; UniProt predicts a signal peptide or a membrane-spanning region.
Gene: Protein-coding gene on chromosome 6 (39,314,698 to 39,322,968, reverse strand). Ensembl gene ENSG00000095981.
Subcellular location: Endoplasmic reticulum membrane (Isoform a); Cell membrane; Endoplasmic reticulum membrane (Isoform b); Mitochondrion inner membrane
Pathways (Reactome):
Muscle contraction: Phase 4 - resting membrane potential
Neuronal System: TWIK-related alkaline pH activated K+ channel (TALK)
Gene Ontology:
Molecular function: identical protein binding; outward rectifier potassium channel activity; potassium channel activity; protein binding; protein heterodimerization activity; potassium ion leak channel activity
Biological process: endoplasmic reticulum calcium ion homeostasis; potassium ion transport; regulation of action potential; regulation of release of sequestered calcium ion into cytosol; membrane repolarization during action potential; regulation of insulin secretion involved in cellular response to glucose stimulus; potassium ion transmembrane transport; regulation of membrane potential
Cellular component: endoplasmic reticulum membrane; plasma membrane; membrane; mitochondrial inner membrane
Genetic constraint (gnomAD): Loss-of-function variants: 23 observed, 22.27 expected, observed/expected ratio (o/e) 1.03, 90% interval 0.74 to 1.46. The upper end of that interval is the gene's LOEUF score, 1.46, which puts it in group 6 of 6, group 1 being the genes least tolerant of losing a copy. Missense variants: 320 observed, 352.65 expected, observed/expected ratio (o/e) 0.91, 90% interval 0.83 to 1. Synonymous variants: 143 observed, 151.23 expected, observed/expected ratio (o/e) 0.95, 90% interval 0.82 to 1.09.
Homologues: Orthologues: chimpanzee KCNK16 (94% identical), dog KCNK16 (90% identical), pig KCNK16 (90% identical), rabbit KCNK16 (88% identical), mouse Kcnk16 (87% identical), rat Kcnk16 (87% identical), macaque KCNK16 (79% identical), guinea pig KCNK16 (77% identical), tropical clawed frog kcnk16 (60% identical), Drosophila melanogaster Ork1 (27% identical), Drosophila melanogaster Task7 (27% identical), Caenorhabditis elegans twk-21 (26% identical), and 10 more. Paralogues in human: KCNK17 (38% identical), KCNK10 (34% identical), KCNK5 (33% identical), KCNK4 (32% identical), KCNK2 (32% identical), KCNK6 (30% identical), KCNK9 (30% identical), KCNK1 (30% identical), KCNK15 (30% identical), KCNK3 (30% identical), KCNK13 (28% identical), KCNK12 (26% identical), and 2 more.
Diseases named in the same sentence as KCNK16 in open-access papers:
KCNK16 is named in the same sentence as 15 diseases in open-access papers, as found by Europe PMC text mining. Sharing a sentence is not in itself a finding about the gene and the disease. The quoted sentences say what the papers report.
maturity-onset diabetes (9 papers, 2017 to 2024). "KCNK16, a known type 2 diabetes susceptibility gene that encodes the potassium channel subfamily K member 16, a pancreatic potassium channel, represents an example of a novel glutamine-associated locus with a role in glucose biology." (PMID 38448586, 2024). "A nucleotide polymorphism in KCNK16 was associated with type 2 diabetes." (PMID 35482723, 2022). "A gain-of-function polymorphism in KCNK16, the gene encoding TALK-1, increases risk for developing type-2 diabetes." (PMID 28403169, 2017). "The KCNK16 mutation causing TALK-1 gain of function results in the inhibition of glucose-stimulated membrane potential depolarization and reduced endoplasmic reticulum Ca2+ storage, leading to a form of maturity-onset diabetes of the young." (PMID 35837307, 2022).
diabetes (7 papers, 2017 to 2025). "As the Japanese KCNK16 MODY family showed a greater insulin requirement compared to the patients from Australian KCNK16 MODY family, diversity in diabetes phenotypes likely occurs with KCNK16 mutations." (PMID 38700926, 2024). "Expression of KCNK16, which encodes TWIK-related alkaline pH–activated K2P (TALK-1), is the most abundant and β cell–selective of all human K+ channel transcripts, and TALK-1 gain-of-function mutations would be predicted to cause diabetes similarly." (PMID 34032641, 2021). "Importantly, sQTLs also affected genes that harbor variants that cause monogenic diabetes (KCNK16, ABCC8, PDX1) or influence T2D risk (THADA, PAM) as well as genes that play a role in T1D pathogenesis (ICA1, PTPRN2, HLA-B)." (PMID 36109769, 2022). "Thus, our data suggest a potentially novel therapeutic target for not only KCNK16-associated MODY but possibly for other forms of diabetes also." (PMID 34032641, 2021). "In adolescence, the timeline of development of MODY-like diabetes in the Kcnk16 L114P (L/P) model is consistent with data from MODY patients." (PMID 38700926, 2024). "Together these data highlight the crucial role of TALK-1 in β-cell function and glucose homeostasis and raises the possibility of TALK-1 inhibition as a druggable target for not only KCNK16-associated MODY but possibly for other forms of diabetes." (PMID 38700926, 2024). "Kcnk16 L114P may not cause a significant β-cell destruction because these mice show sufficient glucose-stimulated insulin secretion to prevent overt diabetes." (PMID 38700926, 2024). "Despite the loss of glucose-stimulated islet electrical activity and Ca2+ entry, Kcnk16 L114P mice do not exhibit a drastic reduction in glucose-stimulated insulin secretion and overt diabetes." (PMID 38700926, 2024).
MODY (5 papers, 2021 to 2025). "Although the two families with Kcnk16 L114P exhibit a MODY phenotype, it remains to be determined if KCNK16 mutations are associated with other diabetic phenotypes besides MODY." (PMID 38700926, 2024). "Taken together, the KcnK16 L114P mouse model shows disrupted glucagon and insulin secretion leading to fasting hyperglycemia and glucose intolerance, which provides confirmation that TALK-1 gain-of-function mutations likely cause MODY." (PMID 38700926, 2024). "Taken together, this study shows that the MODY-associated Kcnk16 L114P mutation disrupts glucose homeostasis in adult mice resembling a MODY phenotype and causes neonatal lethality by inhibiting islet insulin secretion during development." (PMID 38700926, 2024). "Our data suggest TALK-1 as an efficacious and islet-selective therapeutic target for both KCNK16-associated MODY and, potentially, T2DM." (PMID 34032641, 2021). "Here, we have identified a nonsynonymous coding variant in KCNK16 (NM_001135105: c.341T>C, p.Leu114Pro) segregating with MODY." (PMID 34032641, 2021). "Furthermore, the KCNK16 Leu114Pro mutation related to MODY has been found to disrupt glucose regulation in adult mice, leading to a MODY-like phenotype and neonatal mortality by inhibiting insulin secretion in the islets during development." (PMID 40650956, 2025). "Moreover, we recently determined that the MODY-associated Kcnk16 L114P mutation results in a significant gain-of-function in TALK-1 K+ flux." (PMID 38700926, 2024). "Exome sequencing in a family with MODY identifies a previously unreported coding variant in KCNK16." (PMID 34032641, 2021). "In conclusion, we have identified a mutation in KCNK16 that causes a gain of function in TALK-1 and reduces glucose-stimulated Ca2+ influx, Ca2+ER storage, and GSIS, resulting in MODY." (PMID 34032641, 2021). "Both mouse and human islets expressing TALK-1 Leu114Pro exhibited significantly reduced glucose-stimulated insulin secretion compared to those expressing the wild-type, suggesting that KCNK16 May be a novel pathogenic gene for MODY." (PMID 40650956, 2025). "However, we acknowledge that, to date, a further unrelated family with MODY with a pathogenic variant in KCNK16 segregating with MODY phenotype has not been identified to our knowledge." (PMID 34032641, 2021). "We hope that the data presented here may lead to screening of KCNK16 in families with MODY negative for mutations in other known MODY genes, as identification of a second family would further strengthen KCNK16 as a MODY gene." (PMID 34032641, 2021). "Due to the β-cell-intrinsic role of TALK-1 L114P channels, the effect of somatostatin on glucose-stimulated insulin secretion might be limited; however, it remains to be determined if the fasting hyperglycemia observed in KCNK16-MODY patients is due in part to elevated glucagon secretion." (PMID 38700926, 2024).
Hyperglycemia (3 papers, 2021 to 2024). An increased concentration of glucose in the blood. "Specifically, in mice heterozygous for Kcnk16 L114P mutation, we observe neonatal hyperglycemia due to blunted glucose-stimulated insulin secretion, which can additionally result in neonatal death in mice homozygous for the mutant (L114P) allele of Kcnk16." (PMID 38700926, 2024). "Kcnk16 L114P mice show a similar phenotype, with neonatal islets showing a complete loss of glucose-stimulated [Ca2+]c influx, a drastic reduction in glucose-stimulated insulin secretion, and severe hyperglycemia by P4." (PMID 38700926, 2024). "Hyperglycemia in neonatal Kcnk16 L114P mice subsided by P10, when glycemia was equivalent to WT controls." (PMID 38700926, 2024). "Heterozygous Kcnk16 L114P caused almost complete neonatal lethality in the B6 background but only hyperglycemia in the B6:CD-1 background, whereas homozygous Kcnk16 L114P led to neonatal lethality in the B6:CD-1 mice." (PMID 38700926, 2024). "Taken together, this suggests that perturbed Kcnk16 L114P islet-intrinsic (e.g. Ca2+ handling) and -extrinsic (e.g. hyperglycemia) pathways result in direct as well as indirect disruption of islet function." (PMID 38700926, 2024). "Because neonatal Kcnk16 L114P (L/P) mice showed transient hyperglycemia, we next utilized an intraperitoneal glucose tolerance test (GTT) to determine if Kcnk16 L114P impairs glucose homeostasis in young adulthood." (PMID 38700926, 2024). "This indicates that the fasting hyperglycemia observed in male Kcnk16 L114P (L/P) mice is likely a result of the observed increase in glucagon secretion under fasting conditions." (PMID 38700926, 2024). "Moreover, prolonged hyperglycemia (although modest in this model) would also be predicted to result in long-term gene expression changes in Kcnk16 L114P islets that alter β-cell function." (PMID 38700926, 2024). "Adult Kcnk16 L114P mice exhibit fasting hyperglycemia and glucose intolerance." (PMID 38700926, 2024). "Chronic hyperglycemia in diabetic patients and rodents results in islet dysfunction and destruction, thus hyperglycemia observed in the Kcnk16 L114P mice could exacerbate β-cell failure." (PMID 38700926, 2024). "Furthermore, male Kcnk16 L114P (L/P) mice also exhibit fasting hyperglycemia indicating a likely non-β-cell-specific islet defect in this mouse model." (PMID 38700926, 2024). "Other pathways could also be impacted in Kcnk16 L114P islets that may modify Ca2+ handling or respond to the altered signaling such as in response to reduced glucose-stimulated [Ca2+]c influx, fasting hyperglycemia, and/or impaired glucose tolerance." (PMID 38700926, 2024). "Similar to the proband from the human KCNK16 L114P MODY family who showed elevated fasting blood glucose (~7 mM), Kcnk16 L114P mice also exhibit fasting hyperglycemia." (PMID 38700926, 2024). "Lethality is likely a result of severe hyperglycemia observed in the homozygous Kcnk16 L114P neonates due to lack of glucose-stimulated insulin secretion and can be reduced with insulin treatment." (PMID 37546831, 2024). "Although hyperglycemia would be predicted to negatively impact Kcnk16 L114P islet function, no overt changes in β-cell mass were observed in these mice." (PMID 38700926, 2024). "Interestingly, we observe increased neonatal lethality in heterozygous and homozygous Kcnk16 L114P mice in the C57BL/6J (B6) and the B6;CD-1 (ICR) mixed genetic backgrounds, respectively, likely due to severe hyperglycemia and lack of glucose-stimulated insulin secretion." (PMID 38700926, 2024).
Glucose intolerance (1 paper, 2024). Glucose intolerance (GI) can be defined as dysglycemia that comprises both prediabetes and diabetes. "In young adulthood, Kcnk16 L114P causes glucose intolerance due to a reduction in glucose-stimulated insulin secretion mediated by enhanced β-cell Vm hyperpolarization and reduced glucose-stimulated Ca2+ entry." (PMID 38700926, 2024). "Female Kcnk16 L114P (L/P) mice only developed moderate glucose intolerance compared to the controls (WT) in both B6 and B6;CD-1 genetic backgrounds." (PMID 38700926, 2024). "Male Kcnk16 L114P (L/P) mice developed glucose intolerance as early as 11 weeks of age in the B6;CD-1 background and 8 weeks of age in the B6 background compared to their respective control littermates (data not shown)." (PMID 38700926, 2024). "Moreover, the Kcnk16 L114P mutation resulted in greater body weight gain in B6;CD-1 females compared to the WT controls due to increased lean mass, which might reduce glucose intolerance in Kcnk16 L114P (L/P) females compared to males." (PMID 38700926, 2024). "Similar to the timeline of disease progression in other MODY mouse models, Kcnk16 L114P mice developed glucose intolerance during adolescence (~8 weeks in the B6 strain)." (PMID 38700926, 2024). "The onset and severity of glucose intolerance in Kcnk16 L114P mice also recapitulates the data from KCNK16 L114P MODY family probands, who were diagnosed at 11 and 15 years of age and displayed an abnormal oral GTT (blood glucose: 19 and 19.6 mM, 2 hr after 75 g oral glucose bolus, respectively)." (PMID 38700926, 2024).
migraine (1 paper, 2023). "KCNK16, located near lead SNP rs9380862, was revealed as a significant shared locus associated with both migraine and glucose." (PMID 36808568, 2023).
thyroid cancer (1 paper, 2020). "However, KCNK1, KCNK6, KCNK7, KCNK9, KCNK10, KCNK13 and KCNK16 mRNA expressions were not related to the prognosis of patients with thyroid cancer." (PMID 32742463, 2020).
KCNK16 also shares sentences with these, for which no sentence is quoted: amyotrophic lateral sclerosis (1 paper); channelopathy (1); epilepsy (1); Headache (1); Hypoinsulinemia (1); Impaired glucose tolerance (1); maturity-onset diabetes of the young (1); papillary thyroid carcinoma (1).